CD2 (CD2 molecule)
Description:
CD2 interacts with lymphocyte function-associated antigen CD58 (LFA-3) and CD48/BCM1 to mediate adhesion between T-cells and other cell types. CD2 is implicated in the triggering of T-cells, the cytoplasmic domain is implicated in the signaling function.
Synonyms: SRBC; LFA-2; T11
Tractability: Antibody: a drug acting on it is in phase 2 or 3 trials; UniProt places it where antibodies can reach, with high confidence; its Gene Ontology location is reachable by antibodies, with high confidence; UniProt predicts a signal peptide or a membrane-spanning region; the Human Protein Atlas places it where antibodies can reach. PROTAC: ubiquitination databases record sites on it; its protein half-life has been measured; a small molecule that binds it is known. Other modalities: an approved drug acts on it.
Target class: Surface antigen
Gene: Protein-coding gene on chromosome 1 (116,754,370 to 116,769,229, forward strand). Ensembl gene ENSG00000116824.
Subcellular location: Cell membrane
Subcellular location (Human Protein Atlas): Plasma membrane; Golgi apparatus; Nucleoplasm
Pathways (Reactome):
Hemostasis: Cell surface interactions at the vascular wall
Gene Ontology:
Molecular function: protein binding; signaling receptor binding; signaling receptor activity; identical protein binding; protein kinase binding; receptor tyrosine kinase binding
Biological process: heterotypic cell-cell adhesion; natural killer cell activation; natural killer cell mediated cytotoxicity; positive regulation of interleukin-8 production; positive regulation of tumor necrosis factor production; positive regulation of type II interferon production; apoptotic process; cell surface receptor signaling pathway; cell-cell adhesion; immune response; membrane raft polarization; positive regulation of myeloid dendritic cell activation; regulation of T cell differentiation; T cell activation; cell adhesion
Cellular component: cell surface; external side of plasma membrane; plasma membrane; cell-cell junction; cytoplasmic side of plasma membrane; extracellular region; membrane; protein-containing complex
Genetic constraint (gnomAD): Loss-of-function variants: 17 observed, 22.31 expected, observed/expected ratio (o/e) 0.76, 90% interval 0.52 to 1.14. The upper end of that interval is the gene's LOEUF score, 1.14, which puts it in group 5 of 6, group 1 being the genes least tolerant of losing a copy. Missense variants: 415 observed, 430.46 expected, observed/expected ratio (o/e) 0.96, 90% interval 0.89 to 1.05. Synonymous variants: 160 observed, 155.66 expected, observed/expected ratio (o/e) 1.03, 90% interval 0.9 to 1.17.
Homologues: Orthologues: chimpanzee CD2 (99% identical), macaque CD2 (94% identical), rabbit CD2 (62% identical), pig CD2 (58% identical), dog CD2 (56% identical), guinea pig CD2 (55% identical), rat Cd2 (54% identical), mouse Cd2 (52% identical), zebrafish si:cabz01074946.1 (14% identical). Paralogues in human: LY9 (20% identical), SLAMF7 (19% identical), CD84 (17% identical), CD244 (16% identical), SLAMF6 (15% identical), SLAMF1 (14% identical), SLAMF8 (12% identical), SLAMF9 (12% identical), CD48 (9% identical).
Diseases named in the same sentence as CD2 in open-access papers:
CD2 is named in the same sentence as 199 diseases in open-access papers, as found by Europe PMC text mining. Sharing a sentence is not in itself a finding about the gene and the disease. The quoted sentences say what the papers report.
lymphoma (31 papers, 2011 to 2025). A malignant (clonal) proliferation of B- lymphocytes or T- lymphocytes which involves the lymph nodes, bone marrow and/or extranodal sites. "Single cell suspensions from lymphoma tissue were expanded with anti-NKp46/anti-CD2-coated beads in the presence of IL-2." (PMID 31126350, 2019). "Common targets in the Eμ-Myc lymphoma model include Runx1 and Runx3, while all three members of the Runx family were identified as activation targets in CD2-MYC T-cell lymphomas." (PMID 27056890, 2016). "A second RIM/DS screen comparing lymphomas of wild-type and parental transgenics showed that CD2-MYC tumours are virtually dependent on activation of Runx family genes in strong preference to other potent Myc collaborating genes (Gfi1, Notch1)." (PMID 24586197, 2014). "While aberrant T-cell antigen expression has been associated with EBV infection, this has largely been limited to expression of CD2 and CD3 on a subset of pyothorax-associated lymphomas and on EBV-transformed B-cell lines." (PMID 23738160, 2013). "In lymphoma, lymphocytes are more likely to be large and atypical, and they may lack markers CD2, CD3, CD5, and CD7." (PMID 38899272, 2024). "BM flow cytometry gating on the lymphoma cells confirmed the positive expression of CD2, CD3, CD7, CD8, CD56, T‐cell receptor (TCR) alpha‐beta chains, perforin, granzyme B, and negative for CD34, CD4, CD5, and TCR gamma‐delta chains, consistent with natural killer (NK)/T lymphoma involvement." (PMID 37206287, 2023). "Moreover, due to the broad expression of LFA3 on CD2- lymphomas and the important role of CD2 in T cell costimulation, investigators have highlighted the benefit of using CD2 costimulation on CART cells." (PMID 32582179, 2020). "An alternative to anti-CD2 mAbs, CD2-targeting chimeric antigen receptor T cells could be employed for treatment of CD2+ lymphomas." (PMID 32582179, 2020). "Lymphoma cells usually have the following phenotype: CD2+, CD3+, CD4−, CD5−, CD7+ and CD8−." (PMID 23145171, 2012). "Anti-CD2 ITs have been studied as therapies for CD2+ lymphomas and leukemias." (PMID 22069735, 2011). "Patients with CD2+ lymphomas may benefit from depletory anti-CD2 treatments." (PMID 32582179, 2020). "In one study, 10.0% of cases of B-lymphoblastic leukemia/lymphoma expressed one or more T cell antigens: CD4 in 5.0% of cases, CD5 in 2.2% of cases, CD7 in 2.2% of cases, and CD2 in 0.6% of cases." (PMID 40227608, 2025). "T-lymphoblastic leukemia/lymphoma is characteristically positive for T cell markers, including cytoplasmic CD3 (which is lineage-defining and specific), CD5, CD7, and CD2, which can all be assessed by flow cytometric analysis." (PMID 40227608, 2025). "The expression of T cell antigens, including CD2, CD4, CD5, CD7, and monocytic antigens, has also been reported in B-lymphoblastic leukemia/lymphoma." (PMID 40227608, 2025). "The lymphoma cells express T-cell markers, such as cytoplasmic CD3 (CD3ε), CD2, and CD8, as well as the NK-cell marker CD56." (PMID 35783622, 2022). "We showed that CD2 on T cells is associated with directional migration and that the interaction between CD2 on T cells and CD58 on lymphoma cells accelerates killing and serial killing." (PMID 35881486, 2022).
lymphoma (continued). "B-lymphoblastic leukemia/lymphoma with DUX4 rearrangement typically is positive for CD371 and CD2." (PMID 40227608, 2025). "Lymphoma cells in γδHSTCL showed blast-like morphology and were typically positive for moderate CD2, surface CD3, CD7, and TCRγδ, and weak-to-negative CD5." (PMID 35299754, 2022). "The lymphoma cells express CD2 and CD3e, but usually not CD3s or other T-cell markers (CD4, CD5, and CD8)." (PMID 34702349, 2021). "In HSTCL, the lymphoma cells are typically double negative (CD4−CD8−) even if a subset of cases are CD8+, positive for CD3, CD2, CD7, and negative for CD1a and CD5." (PMID 38790955, 2024). "Targeting CD2, therefore, would allow for the effective targeting of a wide variety of CD7 negative or low expression T cell leukemia and lymphomas such as T-ALL, SS, peripheral T cell malignancies, and adult T cell leukemia/lymphoma (ATL)." (PMID 37798328, 2023). "The lymphoma cells were small to medium-sized and resulted as positive, in all patients, for CD3, CD2, CD7, and TIA1 and negative for ALK, CD56, CD57, granzyme-B, and Perforin." (PMID 37345080, 2023). "Lymphoma cells are usually positive for: CD7, CD3, CD2, CD8, CD56 and negative for CD4, CD5, CD30." (PMID 39317016, 2024). "The pathology report indicated no sign of lymphoma in the left capsule or axillary lymph node; however, the fluid from the area surrounding the left implant showed large atypical cells that were positive for CD30, negative for ALK, and negative for CD2, CD3, CD4, CD7, CD8, CD20, CD56, and TIA-1." (PMID 38256500, 2024). "In contrast, in T-lymphoblastic leukemia/lymphoma, the neoplastic cells may be negative for surface CD3 staining or positive, but variable CD3 is usually not observed, and the expression of pan T cell antigens, including CD2, CD5, and CD7, may be absent, but not variable." (PMID 40227608, 2025).
psoriasis (24 papers, 2006 to 2026). An autoimmune condition characterized by red, well-delineated plaques with silvery scales that are usually on the extensor surfaces and scalp. "Alefacept (a lymphocyte function-associated antigen (LFA)-3 Ig fusion protein that binds to CD2 and functions as an antagonist to T-cell activation) has been shown to result in improvement in psoriasis but has limited effectiveness in PsA." (PMID 23006144, 2012). "In human skin, CD2+MHC-II+CCR2+ myeloid precursors were significantly more prevalent in individuals with psoriasis than in healthy control individuals." (PMID 41482544, 2026). "Psoriasis induced proinflammatory CD2+MHC-II+CCR2+ myeloid precursors to migrate from the skin to joints, but their migration alone was insufficient to induce arthritis." (PMID 41482544, 2026). "Alefacept, a recombinant LFA-3/IgG1 fusion protein was previously investigated as an immunosuppressive anti-CD2 treatment for psoriasis, and was noted to selectively deplete memory T cell subsets." (PMID 34035409, 2021). "Dysfunction of CD58 and CD2 in humans results in various diseases, such as multiple sclerosis, rheumatic arthritis, and psoriasis." (PMID 29904386, 2018). "In psoriasis, Tregs frequency was minimally affected after alefacept treatment of 22 psoriasis patients despite high CD2 expression." (PMID 27110598, 2015). "Alefacept, a CD2-binding leukocyte-function associated antigen (LFA)-3 Ig fusion protein has been proposed to clear psoriasis lesions through the depletion of CD2-expressing cells, which includes T cells but also DCs, although to low level." (PMID 21295490, 2011). "Consequently, there was a significant reduction in the percentage of CD2+MHC-II+CCR2+ myeloid precursors interacting with CD200+ fibroblasts in individuals with PsA compared to in those with psoriasis." (PMID 41482544, 2026). "Alefacept (anti-CD2) biologic therapy led to selective reduction of circulating effector memory T cells (Tem) and relative preservation of central memory T cells (Tcm) in psoriasis." (PMID 39480805, 2024). "Next, we induced psoriasis on Cd2-Cre Il27raflox/flox mice with Il27raflox/flox as controls." (PMID 38982043, 2024). "Moreover, FCGR3A was found to interact with known therapeutic targets of psoriasis such as CD2, Tumor necrosis factor (TNF), Integrin subunit alpha L (ITGAL), and IL17A." (PMID 39883516, 2024). "Lastly, although alefacept production has been discontinued due to the availability of other more effective therapies for psoriasis, which is the primary indication of the drug, other biologics targeting CD2 are currently in development for future trials in T1D or the at-risk setting." (PMID 37751304, 2023). "Notably, the effect of the environment on the same disease can be mediated through several distinct subfunction proteins (e.g., THBD and CD2 mediate psoriasis)." (PMID 29689083, 2018). "The modulation of cell surface and activation marker expression by dalazatide treatment suggests that the 60 mcg dalazatide treatment dose engaged the Kv1.3 target on CD2+ memory T cells as well as CD2+CLA+ memory T cells homing to the skin of psoriasis patients." (PMID 28723914, 2017). "Alefacept is a LFA3 fusion molecule that binds CD2 and results in eradication of CD2 expressing cells and has primarily been used in the treatment of psoriasis where it resulted in clinical benefit and sustained disease remission long after drug termination, suggesting lasting immune tolerance." (PMID 26834735, 2015). "Alefacept, a LFA-3/IgG1 fusion protein that binds to CD2, is the first biologic agent approved by the US Food and Drug Administration (FDA) for the treatment of moderate-to-severe psoriasis in 2003." (PMID 34354596, 2021). "Based on immune chemistry, the levels of CD2+, CD4+, CD8+ T-lymphocytes were also found to be raised in both depression and psoriasis, validating their relationship." (PMID 34183985, 2021).
psoriasis (continued). "In psoriasis, activation of T lymphocytes involves interaction between LFA-3 on the antigen-presenting cells and CD2 on T lymphocytes." (PMID 22509259, 2012). "In a trial including 553 patients with psoriasis, a group of investigators evaluated the impact on HRQL of alefacept, a fusion protein that inhibits T-cell activation and promotes apoptosis of CD2+ T cells that play a role in psoriasis, on HRQL." (PMID 16973000, 2006). "Both the CD4+ and CD8+ T cell populations demonstrated attraction to CD2+MHC-II+CCR2+ myeloid precursors in the noninflamed synovia of individuals with psoriasis and the inflamed synovia of individuals with PsA." (PMID 41482544, 2026). "Additionally, the density of CD8+, CD45RO+, CD2+, CD94, and CD161 was found to be markedly reduced in ILVEN versus psoriasis." (PMID 40103681, 2025). "Based on these data and data from psoriasis clinical trials, we speculate that the Tregs in HIV patients will also be preserved, if ART and/or HIV infection does not modulate the CD2 expression levels on their surface." (PMID 27110598, 2015). "We then used imaging mass cytometry (IMC) to detect CD2+MHC-II+CCR2+ myeloid precursors and CD200+ (DKK3+FAP+CD45−CD31−) fibroblasts in the synovial tissues of individuals with early PsA who had just developed arthritis and individuals with psoriasis without arthritis." (PMID 41482544, 2026).
leukemia (22 papers, 2008 to 2025). A malignant (clonal) hematologic disorder, involving hematopoietic stem cells and characterized by the presence of primitive or atypical myeloid or lymphoid cells in the bone marrow and the blood. "Regarding leukemia-associated immunophenotype (LAIP) and prognostic markers, CD56 and CD2 were positive in one case, while cytoplasmic FXIII-A was positive in all cases." (PMID 30830246, 2019). "Tertiary transplant experiments revealed that the human CD45+CD34+CD2+CD7+ population propagated leukemia and seeded hematopoietic niches, which was demonstrative of LIC self-renewal capacity." (PMID 22768113, 2012). "In three-color flow cytometry (FCM), T-LGL leukemia cells demonstrated CD2, CD3, and CD8 expression as well as a combination of CD16, CD56, or CD57." (PMID 18474096, 2008). "Ectopic expression of GATA3 under the control of the CD2 promoter is able to promote T cell transformation suggesting that this failure to repress Gata3 could be a key event in the generation of E2a-/- leukemias." (PMID 35514954, 2022). "To compare tissue oxygenation and T cell dynamics in healthy BM to that in BM with acute lymphoblastic leukemia (ALL), we infused the immune competent CD2-DsRed/CD11c-YFP dual fluorescent mice with syngeneic cyan-fluorescent leukemia cells transformed by the BCR-Abl fusion protein expression." (PMID 30885258, 2019). "In the CD2-Lmo2 transgenic (Lmo2Tg) model of ETP-ALL, leukemia arises from an expanded CD4-CD8-CD44-CD25+CD28- (DN3a) thymocyte population, which contains preLSCs that display a stem-like phenotype." (PMID 39849166, 2025). "The cCD3par+CD7bri+CD2+ expression profile and TCR-γ rearrangement in one of the populations are in accordance with the T-lymphoblastic leukemia phenotype." (PMID 36199105, 2022). "The leukemia-containing clusters were found to have a low expression of CD48 and CD58, the genes coding for activating ligands that bind CD2." (PMID 35349491, 2022). "Representative FACS analysis showed the evidence of development of a biphenotypic CD2+CD11b+ and GFP+ leukemia." (PMID 26568842, 2015). "The typical immunophenotype of T-LGL leukemia cells was CD45+bright, CD2+bright, CD3+bright, CD4-, CD8+bright, CD25-, and CD43+weaker." (PMID 18474096, 2008). "Other positive markers were CD2/5/7 associated with CD8 expression without CD1a, therefore consistent with ALL pre-T/T (ALL-European Group of Immunological Markers for Leukemias scoring of TII/TIII)." (PMID 35334633, 2022). "In 22/24 recipients injected with hCD45+ G+C+ cells (FACS sorted from day 24–25 N+ LTB-transduced CB cultures), we obtained G+C+ leukemias of T-cell lineage, typically CD7+ CD2+ sCD3+/− CD1a+/− and variable CD4/CD8 pattern including CD4− CD8− (DN), CD4+ CD8+ (DP), and CD4− CD8dim (SP8dim)." (PMID 31266935, 2019). "The striking similarities between CD2-Lmo2 transgenic T-ALLs and human T-ALL suggest that these transgenic mice are a compelling mouse model of human disease, one that will prove useful in studying a highly treatment-resistant leukemia." (PMID 24465765, 2014). "In our case, however, the leukemia cells was found negative for CD2, CD5 and CD7, making aberrant expression of AML relatively unlikely." (PMID 22356850, 2012). "Therefore, while it is not surprising that MCIA identified CD2 as a leukemia specific receptor in comparison to all the other cancer entities, it is conceivable that CD2 is not a tumor marker." (PMID 36221114, 2022).